KLF5 (KLF transcription factor 5)
Diseases named in the same sentence as KLF5 in open-access papers (continued):
Sharing a sentence is not in itself a finding about the gene and the disease.
KLF5 also shares sentences with these, for which no sentence is quoted: pituitary adenoma (3 papers); liver (2); lupus nephritis (2); metabolic disease (2); neuroblastoma (2); oral squamous cell carcinoma (2); acute myocardial infarction (1); atrophic gastritis (1); B-cell lymphoblastic leukemia (1); B-cell lymphomas (1); Barrett esophagus (1); bile reflux (1); bladder urothelial carcinoma (1); cholangiocarcinoma (1); clear cell renal cell carcinoma (1); Cognitive impairment (1); colorectal tumors (1); congestive heart failure (1); cutaneous melanoma (1); diabetic neuropathy (1); dilated cardiomyopathy (1); duodenogastric reflux (1); dyslipidemia (1); ectodermal dysplasias (1); endometrioid adenocarcinoma (1); gallbladder cancer (1); gastritis (1); Gastroesophageal reflux (1); gastrointestinal disorders (1); Glucose intolerance (1).
A further 39 diseases each share a sentence with KLF5 in 1 paper.